DEK (DEK proto-oncogene)
Diseases named in the same sentence as DEK in open-access papers (continued):
Sharing a sentence is not in itself a finding about the gene and the disease.
glioblastoma (5 papers, 2013 to 2025). The most malignant astrocytic tumor (WHO grade IV). "DEK was found to be highly expressed in astrocytic tumors, and DEK silencing in glioblastoma cells in vitro inhibited cell proliferation and induced apoptosis." (PMID 36275000, 2022).
head and neck cancer (5 papers, 2015 to 2020). A primary or metastatic malignant neoplasm affecting the head and neck. "Specifically, we analyzed the TCGA provisional head and neck cancer study, and only 2 out of 530 tumors harbored mutations within the DEK gene." (PMID 28423581, 2017). "Furthermore, DEK mRNA and protein upregulation are present in both cervical and head and neck cancer specimens, further supporting the importance of continued DEK expression in these cancers." (PMID 26425120, 2015).
lung carcinoma (5 papers, 2020 to 2025). "DEK also promoted the proliferation and invasion of lung cancer cells A549 and H1299 through β‐catenin and Wnt signalling pathways." (PMID 33124760, 2020). "Indeed, DEK overexpression in vitro was associated with an increase in EGFR, KRAS, and vimentin levels in lung cancer cell lines and poor prognosis according to patient database analyses." (PMID 39852534, 2025).
colorectal cancer (4 papers, 2013 to 2023). A primary or metastatic malignant neoplasm that affects the colon or rectum. "And DEK expressions in epithelial cells are correlated with FBXW7 mutations in human colorectal cancer." (PMID 23902796, 2013). "To further substantiate the importance of high DEK expression in colorectal cancer progression, we compared its effect on prognosis by analyzing the correlations between DEK expression and factors associated with aggressiveness of colorectal cancer." (PMID 23902796, 2013). "Our previous study reported that high DEK expression is associated with serosal invasion, lymph node metastasis, tumor size and differentiation, which are crucial histological features associated with poor prognosis in colorectal cancer." (PMID 24650035, 2014). "Moreover, multivariate analysis showed high DEK expression, serosal invasion, and late stage are significant independent risk factors for mortality in colorectal cancer." (PMID 23902796, 2013). "We also previously found that DEK was significantly overexpressed in colorectal cancers and that the expression correlated to poor prognostic factors with colorectal cancers." (PMID 24650035, 2014). "Our previous study showed that the strongly positive rate of DEK protein was 48.62% (53/109) in colorectal cancers, which was significantly higher than that in either adjacent normal colon mucosa (9.17%, 10/109) or colorectal adenomas (13.46%, 7/52)." (PMID 25340858, 2014). "Our previous study indicated that DEK protein was overexpressed in colorectal carcinoma (CRC) compared with the normal colorectal mucosa." (PMID 25340858, 2014). "For the TNM and FIGO clinical stages, the strongly positive rate of DEK protein was 62.00% (31/50) in the advanced stage (IIB–IIIC) colorectal cancers, but only 37.29% (22/59) in early stage cases (I–IIA) (P=0.010)." (PMID 23902796, 2013). "In conclusion, we have identified DEK as a potential biomarker for evaluation of tumor progression and prognosis of colorectal cancers." (PMID 23902796, 2013). "This is the first study, to our knowledge, to correlate DEK levels in colorectal cancers with histological prognostic factors to understand the role of DEK up regulation in colorectal cancer progression." (PMID 23902796, 2013). "The strongly positive rate of DEK protein was significantly higher in colorectal cancers with >5 cm tumor size than in cases with ≤5 cm tumor size (P=0.029)." (PMID 23902796, 2013). "Our data uncovered that DEK is frequently upregulated in colorectal cancers when compared with either the normal tissues counterparts or colorectal adenomas." (PMID 23902796, 2013). "To evaluate the relationship between DEK protein and colorectal cancer progression, we analyzed the correlation between DEK protein over expression and clinicopathological features of colorectal cancers." (PMID 23902796, 2013). "The positive rate of DEK protein expression was significantly higher in colorectal cancer tissues (95.41%, 104/109) than in either normal adjacent mucosa (33.03%, 36/109) or colorectal adenomas (32.69%, 17/52)." (PMID 23902796, 2013). "The strongly positive rate of DEK protein was 48.62% (53/109) in colorectal cancers, which was significantly higher than that in either adjacent normal colon mucosa (9.17%, 10/109) or colorectal adenomas (13.46%, 7/52)." (PMID 23902796, 2013). "Of particular interest, high DEK expression was found to be an independent hazard factor in colorectal cancer." (PMID 23902796, 2013). "This study explores the roles of DEK in tumor progression and as a prognostic determinant of colorectal cancer." (PMID 23902796, 2013). "DEK plays an important role in the progression of colorectal cancers and it is an independent poor prognostic factor of colorectal cancers." (PMID 23902796, 2013). "Here we demonstrate that DEK over expression correlated with large tumor size, low differentiation, serosal invasion, lymph node metastasis, and late-stage in colorectal carcinomas." (PMID 23902796, 2013).
colorectal cancer (continued). "DEK protein expression showed a nuclear immunohistochemical staining pattern in colorectal cancers." (PMID 23902796, 2013). "Importantly, DEK over expression emerged as a significant independent prognostic factor in colorectal cancer (HR: 1.805, 95% CI: 1.208–2.699, P=0.004)." (PMID 23902796, 2013). "Similarly, the strongly positive rate of DEK protein was 48.62% (53/109) in colorectal cancers, which was significantly higher than that in either adjacent normal colon mucosa (9.17%, 10/109) or colorectal adenomas (13.46%, 7/52) (P<0.01, respectively)." (PMID 23902796, 2013). "DEK protein showed a nuclear immunohistochemical staining pattern in colorectal cancers." (PMID 23902796, 2013). "Importantly, we demonstrated that colorectal cancer with high DEK expression correlated with late-stage tumors." (PMID 23902796, 2013). "Our previous data showed that DEK protein was strongly positive in colorectal cancers and dysplastic adenoma of colon, but negative in adjacent normal mucosa, demonstrating that DEK protein expression levels might be used as a biomarker for early diagnosis of colorectal cancers." (PMID 24650035, 2014). "However, the over expression of DEK protein was not related with gender, age, tumor location or CEA levels of patients with colorectal cancer." (PMID 23902796, 2013).
pancreatic cancer (4 papers, 2017 to 2025). "DEK overexpression has been correlated with tumor size and stage in pancreatic tumors, as well as with the probability of metastasis." (PMID 39852534, 2025). "DEK was found to involve in the development of pancreatic cancer as a target of miR-200a." (PMID 34594378, 2021).
papilloma (4 papers, 2013 to 2025). A benign epithelial neoplasm that projects above the surrounding epithelial surface and consists of villous or arborescent outgrowths of fibrovascular stroma. "DEK protein predominantly showed a nuclear staining pattern with slight cytoplasmic staining in normal epithelium, papilloma, CIS, and OSCC tissues." (PMID 28834425, 2017). "Papillomas ultimately formed in the DEK knockout mice, suggesting a role for DEK in tumor initiation in this model." (PMID 24353627, 2013). "Moreover, Trisha, et al5 used littermate DEK knockout, heterozygous and wild type mice for their experiments, and found that there was a significant delay in the formation of papillomas in DEK knockout mice compared to wild type and heterozygous mice." (PMID 24353627, 2013). "Histopathological evaluation revealed that DEK::AFF2 carcinomas frequently exhibit a complex architecture, including endophytic and exophytic, often papilloma-like growth patterns." (PMID 40688086, 2025). "DEK expression in dysplasia/CIS and invasive SCC were increased compared with normal and papilloma in 4NQO‐oral carcinogenesis like humans." (PMID 28834425, 2017). "To investigate the relationship between DEK expression and OSCC in humans, we performed IHC for DEK protein in human normal mucosa adjacent to OSCC (n = 5), papilloma (hyperplasia; n = 12), CIS (n = 16), and OSCC (n = 34)." (PMID 28834425, 2017).
asthma (3 papers, 2020 to 2025). "Conclusively, DEK deficiency alleviates airway inflammation in asthma by down-regulating PINK1-Parkin mitophagy, NLRP3 inflammasome activation, and apoptosis." (PMID 38274803, 2023). "Despite the known associations of DEK with inflammation and asthma, the role of DEK in AR remains unclear." (PMID 39668431, 2025). "Studies on DEK and asthma have revealed the involvement of DEK in regulating mitochondrial structure and function." (PMID 39668431, 2025). "First, immunofluorescence showed that the co-localization of ATAD3A and mitochondria was enhanced after rmDEK intervention in DEK wild-type mice with HDM-induced asthma, and the co-localization was attenuated after in DEK knockout mice." (PMID 38274803, 2023). "Therefore, in future studies, we will investigate the effect of DEK in airway epithelial cells using the Cre-LoxP system or other cell-specific knockout methods to reveal its specific role in the pathogenesis of asthma." (PMID 38274803, 2023). "Given the important role of the MAPK pathway in airway remodelling, we hypothesize that silencing DEK may inhibit EMT inhibition via MAPK pathway during airway remodelling of severe asthma." (PMID 33124760, 2020). "However, the mechanism of DEK on mitophagy in asthma has not been fully understood." (PMID 38274803, 2023). "However, the regulation of PINK1-Parkin-mediated mitophagy by DEK in asthma remains largely unknown." (PMID 38274803, 2023). "Thus, DEK may regulate airway inflammation in asthma by managing the mtROS, NLRP3 inflammasome, and apoptosis of airway epithelial cells." (PMID 38274803, 2023). "Herein, we investigated the regulation of DEK on the PINK1-Parkin pathway, NLRP3 inflammasome, and apoptosis in the HDM-induced asthma model." (PMID 38274803, 2023). "Our previous studies have demonstrated that DEK protein was highly expressed in asthma and DEK-targeting aptamer DTA-64 or miRNA-181b-5p inhibited airway inflammation and airway remodeling in asthma." (PMID 38274803, 2023). "The role of DEK on mitophagy, NLRP3 inflammasome, and apoptosis of asthma model was further verified in DEK-knockout mice." (PMID 38274803, 2023). "This study is the first to identify a hitherto uncharacterized mechanism, i.e. the DEK/ATAD3A/DRP1 signaling axis, by which DEK promotes PINK1-Parkin mitophagy, NLRP3 inflammasome activation, and aggravates airway inflammation in asthma." (PMID 38274803, 2023). "In this study, we used DEK‐targeting aptamer as DEK inhibitor and investigated its role in airway inflammation and EMT in OVA (ovalbumin)‐induced mouse model of asthma." (PMID 33124760, 2020). "The results showed that inhibition of DEK significantly alleviated the bronchial EMT process both in vivo and in vitro, and balanced the Th1/Th2/Th17 immune response in asthma model mice." (PMID 33124760, 2020). "DEK gene knockout, silencing, and targeted inhibitors down-regulated PINK1-Parkin-mediated mitophagy, NLRP3 inflammasome activation, and apoptosis, thereby improving airway inflammation in asthma." (PMID 38274803, 2023). "In mice with HDM-induced asthma, ATAD3A protein and mRNA were reduced in the DEK-/- group." (PMID 38274803, 2023). "Therefore, targeting DEK to downregulate PINK1-Parkin-mediated mitophagy may offer an effective approach for preventing and treating airway inflammation in asthma." (PMID 38274803, 2023).
dementia (3 papers, 2020 to 2025). Loss of intellectual abilities interfering with an individual's social and occupational functions. "Future studies should investigate sex-specific effects of DEK loss, the relationship between DEK and Aβ, the association between AD risk factors and DEK expression, and the effect of DEK loss in specific brain regions and cell types on phenotypes of dementia." (PMID 36275000, 2022). "Before the current study, we found that AD and dementia are candidate DEK loss-associated diseases and that DEK expression decreased with dementia severity in elderly women." (PMID 33304240, 2020). "Given that at normal levels, DEK functions to promote cellular health, we postulate that nuclear DEK could be neuroprotective and that the loss of DEK is related to dementia and AD." (PMID 36275000, 2022). "Here, we have identified DEK as a novel player in dementia and AD by showing that DEK loss could lead to hyperphosphorylated Tau accumulation and apoptosis." (PMID 33304240, 2020). "We hypothesized that DEK loss in vitro would result in cellular and molecular signatures of dementia and AD." (PMID 33304240, 2020). "Therefore, multiple mechanisms of Tau pathology should be investigated in relation to DEK to gain a better understanding of DEK’s role in dementia and AD." (PMID 36275000, 2022). "There is increasing evidence to suggest that DEK expression is protective in neuronal cells and that the regulation of DEK expression could be important in the context of dementia." (PMID 36275000, 2022). "Based on the link between decreased DEK expression to AD phenotypes in human cell models and the selective decrease of DEK in elderly women living with dementia, we hypothesized that female Dek KO mice would exhibit behaviors indicative of cognitive dysfunction." (PMID 41282170, 2025). "Previously, we reported that DEK is expressed in hippocampal neurons and that DEK protein levels are lower in the brains of elderly women with dementia, but not age-matched men." (PMID 33304240, 2020). "Also, using human postmortem brain samples we found that lower DEK protein expression in the anterior cingulate cortex was correlated with increasing dementia severity in women, but not men." (PMID 33304240, 2020).
gastric adenocarcinoma (3 papers, 2014 to 2022). "Although DEK has been shown to be overexpressed in gastric adenocarcinoma, the detailed mechanisms of how DEK is regulated in GC and how DEK affects the disease remain largely unclear." (PMID 35742899, 2022).
sinonasal carcinomas (3 papers, 2022 to 2025). "Follow-up imaging in July 2024, using PET-CT, demonstrated complete metabolic remission of the DEK::AFF2 fusion-associated sinonasal carcinoma." (PMID 40688086, 2025). "However, the deceptively bland histological features raise critical challenges in distinguishing DEK::AFF2 fusion-associated sinonasal carcinomas from inverted sinonasal papillomas based solely on morphology." (PMID 40688086, 2025). "With the recognition of a larger cohort of skull base and sinonasal carcinomas that harbor DEK::AFF2 fusions and confirmation that a subset lacks other known oncogenic mutations, our study solidifies the role of this unique genetic event as the key driver of these tumors." (PMID 38429827, 2024).
acute leukemia (2 papers, 2019 to 2020). A clonal (malignant) hematopoietic disorder with an acute onset, affecting the bone marrow and the peripheral blood. "Chromosomal translocations fusing the locus of nucleoporin NUP214 each with the proto-oncogenes SET and DEK are recurrent in, largely intractable, acute leukemias." (PMID 32934780, 2020). "Chromosomal translocations involving the NUP214 locus are recurrent in acute leukemia and frequently fuse the C-terminal region of NUP214 with SET and DEK, two chromatin remodeling proteins with roles in transcription regulation." (PMID 30669574, 2019).
acute promyelocytic leukemia (2 papers, 2017 to 2023). An aggressive form of acute myeloid leukemia (AML), characterized by arrest of leukocyte differentiation at the promyelocyte stage, due to a specific chromosomal translocation t(15;17) in myeloid cells. "Importantly, PCR assays have been developed for three AML phenotypes: (i) acute promyelocytic leukemia (APL) (fusion gene PML::RARA); (ii) patients with NPM1 and CBF–AML (RUNX1::RUNX1T1 and CBFB::MYH11); and (iii) AML with fusion genes BCR::ABL1, KMT2::MLLT3, and DEK::NUP214." (PMID 37345204, 2023).
ataxia telangiectasia (2 papers, 2007 to 2017). Ataxia-telangiectasia is the association of severe combined immunodeficiency (affecting mainly the humoral immune response) with progressive cerebellar ataxia. "Evidence that DEK regulates key genomic responses to DNA damage was demonstrated by the ability of a partial fragment of DEK, isolated by a cDNA library screen, to complement an ataxia-telangiectasia phenotype in vitro." (PMID 17397536, 2007).
Autoimmunity (2 papers, 2007 to 2017). The occurrence of an immune reaction against the organism's own cells or tissues. "It is necessary to consider the potential role of extracellular DEK in the tumor microenvironment, immunity, and/or autoimmunity and the function of both intracellular and extracellular DEK will be needed to be studied further in order to develop targeted therapies." (PMID 28834425, 2017).
cognitive decline (2 papers, 2024 to 2025). "The DEK allele putatively associated with cognitive decline in AD might therefore improperly regulate DEK levels and perturb proper synaptic homeostasis and tau regulation." (PMID 38462574, 2024).
colorectal adenocarcinoma (2 papers, 2013 to 2014). The most common type of colorectal carcinoma. "Here we performed immunohistochemical staining of DEK protein and survival data analysis using 52 of colon adenomas and 109 of colorectal adenocarcinomas and their adjacent normal tissue counterparts." (PMID 23902796, 2013).
colorectal adenoma (2 papers, 2013 to 2014). An adenoma that arises from the colon or rectum. "In this work, western blot and IHC staining analyses showed that high DEK expression was significantly more common in CRC tissues than in either adjacent normal colorectal mucosa or colorectal adenomas." (PMID 25340858, 2014). "Similarly, the strongly positive rate of DEK protein was 50.9% (28/55) in CRCs, which was significantly higher than in adjacent normal colon mucosa (18.2%, 4/22) and in colorectal adenomas (16.7%, 3/18) (Both P<0.001)." (PMID 25340858, 2014). "The number of cells containing DEK protein (positive rate) was significantly higher in CRC tissues (80.0%, 44/55) than in normal adjacent mucosa (36.4%, 8/22) and in colorectal adenomas (16.7%, 3/18)." (PMID 25340858, 2014).
cutaneous melanoma (2 papers, 2017 to 2024). A primary melanoma arising from atypical melanocytes in the skin. "Transcriptomic, proteomic, and RNA-immunoprecipitation studies, together with loss-of-function analyses and evaluation of patient prognosis, confirmed the relevance of CELF1 as a driver of cutaneous melanoma, with the oncogene DEK as a signal amplifier." (PMID 29269732, 2017). "CELF1 has been implicated as a key driver in skin melanoma and functions as an oncogene by amplifying the signaling effect of DEK SpecificallyCELF1 achieves this by binding to the GU-rich 3' UTR region of DEK mRNA, which leads to an extended half-life of DEK mRNA." (PMID 38443798, 2024).